PCA3 (prostate cancer associated 3)
Diseases named in the same sentence as PCA3 in open-access papers (continued):
Sharing a sentence is not in itself a finding about the gene and the disease.
cancer (continued). "Increased PCA3 levels have also been found in other cancers such as choriocarcinoma as well as ovarian and thyroid cancer, indicating involvement of PRUNE2 in the pathogenesis of these cancers." (PMID 36900197, 2023). "In this regard, ANRASSF1, PCA3 (NCT01024959), HULC (DRKS00017517), CCAT1 (NCT04269746), H19 (NCT04767750), ANRIL, MALAT1 are currently in clinical trial (trial number given in brackets) for cancer patients." (PMID 36428681, 2022). "Therefore, based on the previous reports, in our study, we aimed to figure out the potential of six urinary-exosome-originated cancer-related RNAs (ERG, PSMA, ARA7, PCA3, CK19, and EpCAM) in being biomarkers for the detection and prognosis of PCa." (PMID 35402423, 2022). "Finally, A-to-I editing on the lncRNA prostate cancer antigen 3 (PCA3) enhanced its ability to bind and suppress the PRUNE2 pre-mRNA, thus promoting cancer cell proliferation, adhesion and migration." (PMID 33564819, 2021). "Several genes involved in the progression of PCa, suchas the Prostate Cancer Associated 3 (PCA3), theFos-related antigen 1 (Fra-1) and theProstate Specific Antigen (PSA), presentdifferent expression levels in individuals with and without cancer." (PMID 32154827, 2020). "PCA3 and other PCA molecular tests can potentially reduce overtreatment of insignificant cancers." (PMID 29988684, 2018). "Some autophagy-modulated lncRNAs described in this review are very specific with identical tissue types, for example HULC, PCA3, PVT1 may serve as a potential biomarkers and target therapy in identical cancer types." (PMID 30693021, 2018). "Here we test the predictive role of PCA3-shRNA2 in men with and without PCa, whose initial biopsy did not detect cancer." (PMID 28380027, 2017). "PCA3 and TMPRSS2:ERG had additional independent predictive value for the prediction of PCa detection and progression, although PCA3 was limited in predicting aggressive cancer." (PMID 26339615, 2015). "Unfortunately, PCa patients number is not enough to evaluate the ability of phi and PCA3 alone or in combination to predict clinically localized cancer compatible with watchful waiting." (PMID 23861782, 2013). "The cancer cells (except LuCaP49) could be distinguished by their expression of any one of the cancer genes AMACR, PCA3, AGR2; their expression levels were variable." (PMID 21605402, 2011). "In contrast, others have been shown to be most useful in determining which patients needs to be re-biopsied due to the initial biopsy being negative for cancer despite continued high clinical suspicion for occult cancer: PCA3, TMPRSS2-ERG, ExoDx Intelliscore, Select MDx, and ConfirmMDx." (PMID 36768533, 2023). "Therefore, the 37-gene signature in urine samples represents prostate tissue gene expression and might be useful to distinguish advanced PCa (higher PCA3 and KLK3 levels in cancer) as well as to detect PCa itself." (PMID 32111915, 2020). "Thus, it is plausible that 2–3 years before the diagnosis of cancer, PCA3-shRNA2 expression is not elevated, as the target mRNAs (such as COPS2 and SOX11) do not have, as yet, altered function in the prostate." (PMID 28380027, 2017). "Similarly, PCA3 failed to predict high grade cancers with magnetic resonance imaging (MRI) suspicion score (mSS4-5) in the initial biopsy." (PMID 28881605, 2017). "However, TMPRSS2-ERG is absent in 50% of cancers, and therefore it must be multiplexed with other biomarkers such as PCA3." (PMID 29682400, 2017). "In this study, neither PHI nor PCA3 added to the value of mpMRI in predicting cancers." (PMID 27748407, 2016). "Moreover, the PCA3-3STA is more specific for PCa cells than are the previously introduced MUC1, PSA, PEG-3 and hTERT promoter-based expression systems that can be active in many tissues or cancer subtypes." (PMID 26594800, 2016).
cancer (continued). "The role of PCA3 in clinical practice as a commercially-available test remains uncertain with most advocates indicating a place in patients who have already had TRUS biopsies with a negative result for cancer but in whom PCa remains suspected." (PMID 24281110, 2010). "On the other hand, a negative PCA3 detection in cancer patients may also suggest that the tumor is organ confined." (PMID 18823560, 2008). "This may give PCA3 a cancer specificity that may be lacking with PSA." (PMID 36246565, 2022). "In comparison to PCA3, PHI prevents a higher number of unnecessary biopsies without sacrificing the identification of high-grade cancer." (PMID 36672713, 2023). "The results of the differential gene expression test indicated higher expression of PCA3 and PSMA in the PCa patient group, suggesting that cancer cells could be detected in voided urine without DRE." (PMID 34771706, 2021). "The assays, including PCA3, TMPRSS2-ERG, ExoDx Intelliscore, Select MDx, and Confirm MDx, have potential for patients who need to be re-biopsied, where the initial biopsy was found to be negative for cancer." (PMID 31013716, 2019). "However, the clinical context of the PCA3 assay is to guide further investigation in men with an elevated serum PSA, whose PBx do not reveal cancer." (PMID 28380027, 2017). "The majority of such biomarker tests, including the PCA3 test (PCA3 and KLK3), MiPS (serum PSA plus urine TMPRSS2:ERG and PCA3) and ExosomeDX Prostate Intelliscore (ERG, PCA3, SPDEF), rely on detecting transcripts from a very small number of genes which may not be expressed in every cancer." (PMID 34833048, 2021).
tumor (101 papers, 2008 to 2025). "Up to now, urinary PCA3 represents the sole FDA-approved molecular tumor diagnostic assay derived from ncRNA (PRO-GENSA PCA3)." (PMID 38681199, 2024). "The intriguing association between PCA3 and prostatic carcinoma in human males is at odds with the established concept that oncogenes are shared among different tumor types and/or animal species." (PMID 28751581, 2017). "Next, we explored the association of PCA3 expression (low vs. high) with pathological tumor characteristics, including pathological stage and Gleason group." (PMID 28881605, 2017). "lncRNAs H19, MALAT1, and PCA3 are highly expressed tumor-associated lncRNAs that were characterized before the availability of next generation sequencing technologies." (PMID 28634418, 2017). "Additionally, overexpression of PCA3, a non-coding RNA biomarker, has been associated with increased tumor aggressiveness and is already used clinically for diagnostic decision-making." (PMID 41375053, 2025). "Moreover, the PCA3 test showed a prognostic value, as higher PCA3 score values are associated to a greater tumor aggressiveness." (PMID 25651917, 2015). "However, while association between PCA3 level and tumor size and aggressiveness is encouraging, it remains to be proven that patients with low PCA3 levels can be safely observed." (PMID 27351008, 2014). "Urinary PCA3 was associated with tumor volume, positive margins, tumor stage, and Gleason score." (PMID 22970379, 2012). "However, in the recently conducted multi-institutional Canary Prostate AS Study (n = 387), PCA3 score was significantly associated with a higher biopsy Gleason score and tumor volume, assessed by the percentage of positive cores, in subsequent biopsies (P < 0.01 for all comparisons)." (PMID 26339615, 2015). "Serum miR−141, miR−375, and urine miR−141, miR−375, and PCA3 lncRNA, also showed remarkable correlations with PCa Gleason score (GS), tumor stage, and metastatic status." (PMID 41340217, 2025). "Compared to adjacent marginal tissues, the tumor tissue of patients with GC showed a significant increase in the expression levels of PCA3 and CBR3-AS1 (P < 0.0001)." (PMID 40356687, 2025). "As shown inFig 4C and4D,PCA3, an established PCa marker, was highly expressed in the LE_AR_lo subtype, so we assigned LE_AR_lo as tumor cells but LE-AR-hi as normal luminal cells." (PMID 38808547, 2024). "We next explored the association between biochemical recurrence and tumor expression levels of PRUNE2, PCA3, and the ratio of PRUNE2 to PCA3 expression by using several approaches." (PMID 36645410, 2023). "In that large cohort study, lower levels of tumor PCA3 in both biopsy and radical prostatectomy specimens were associated with high-grade tumors, and in radical prostatectomy specimens decreased PCA3 expression was associated with features of higher stages." (PMID 36645410, 2023). "(B, C) PCA3 expression in the cohort from TCGA (n=497) across Gleason grades (B) showing lower expression in higher grade (>7) tumors and across tumor stages (C) showing lower expression in higher stage tumors." (PMID 36645410, 2023). "We compared the tumor gene expression of PCA3 and PRUNE2 to their corresponding expression in the normal prostate." (PMID 36645410, 2023). "ERG+ tumor cells were characterized by expression of ERG and tumor markers PCA3, AMACR, and TRPM8;35–37ERG− tumor cells were marked by the expression of tumor markers PCA3 and TRPM835–37." (PMID 35013146, 2022). "In vivo, shRNA mediated knockdown of PCA3 significantly inhibited tumour growth of PC3 xenografts and reversed the oncogenic effect of antagomir inhibition of miR-218-5p." (PMID 35159022, 2022). "Microarray analysis identified PCA3 is increased in PCa patient tumours compared to adjacent benign tissues." (PMID 35159022, 2022).
tumor (continued). "Higher expression of tumor-derived RNA biomarkers (PCA3 and PSMA) was observed in the PCa patients compared to those of BPH patients, in agreement with findings above." (PMID 34771706, 2021). "In contrast, both prostate-related (AR and KLK3) and tumor-derived (PCA3 and PSMA) genes were successfully detected in 780 LNCaP or 22Rv1 and 78 22Rv1 cells." (PMID 34771706, 2021). "In fact, 49 of 52 samples have a logtwo-fold change increase in PCA3 expression in the tumor sample compared with its adjacent normal." (PMID 32142370, 2020). "As its plasma expression levels draw a parallel with tumor aggressiveness, as categorized by the Gleason score, circulating PCA3 can also reveal the aggressiveness of PCa." (PMID 31850193, 2019). "The NanoString assay revealed that all DE-kupl contigs were expressed at a lower level than PCA3, but still 21 of 23 contigs were significantly overexpressed (Wilcoxon P-value < 0.01) in tumor specimens." (PMID 31732695, 2019). "It was also reported that PCA3, TMPRSS2:ERG and PHI were predictors of a tumor volume ≥0.5 mL, although multifocality was only predicted by PCA3 score, in patients who underwent RP for biopsy-proven PCa." (PMID 31762940, 2019). "It was reported that PCA3 levels, as well as Prostate Health Index (PHI) and sarcosine levels, were positively associated with some prognostic markers, as tumor volume ≥0.5 mL, pathologic GS ≥7 and pT3 disease." (PMID 31762940, 2019). "Over-expression of PCA3 was significantly higher in tumor compared to the adjacent non-tumor tissue in patients with the 11/11 (P = 0.0322) and 11/12 (P = 0.0013) genotypes." (PMID 29203868, 2017). "Significant over-expression of PCA3 was observed in tumors compared to the adjacent non-tumor tissue in patients with the 11/11 and 11/12 TG-PCA3 genotypes." (PMID 29203868, 2017). "In this study, we utilize the large collection of biopsy and RP expression profiles from the Decipher GRID database (GenomeDx Biosciences Inc.)to study PCA3 expression and link it to clinical data and differentiation levels of tumor." (PMID 28881605, 2017). "Being located in the intronic antisense region of prune homolog 2 (PRUNE2) gene, PCA3 also modulates expression of this tumour suppressor." (PMID 28241429, 2017). "We developed a four-gene expression signature (HIST1H2BG, SPP1, ELF3 and PCA3) with a sensitivity of 77 % and a specificity of 67 % (AUC = 0.763) for discriminating between tumor and control urines." (PMID 26856686, 2016). "Although we currently have a good understanding of the role of PCA3 in tumor genes and tissues, the picture is incomplete." (PMID 27161545, 2016). "Circulating tumour cells (CTCs) have been used as blood-based predictor of distant PCa metastasis; and urinary expression of prostate cancer antigen 3 (PCA3), sarcosine and TMPRSS2:ERG fusion are also emerging markers of PCa risk stratification." (PMID 26885621, 2016). "In patients with high PCA3 score tumor detection rate was high and statistically significant (p=0.0001) (Table-2)." (PMID 27286106, 2016). "The possibility of using the PCA3 test as a prognostic marker is desirable, but the possibility to evaluate tumor aggressiveness by the PCA3 test is openly debated." (PMID 25651917, 2015). "Until now, only a few circulating lncRNAs (for example, PCA3 and HULC) have been identified and have been determined to be good tumor diagnostic markers." (PMID 26674525, 2015). "We confirm a number of previously published molecular changes associated with high risk disease, including MYC amplification, and NKX3-1, RB1 and PTEN deletions, as well as over-expression of PCA3 and AMACR, and loss of MSMB in tumour tissue." (PMID 26501111, 2015).
tumor (continued). "To date, many studies have been performed and most of them showed how the PCA3 test represents a useful tool to predict PCa, but questions about the optimal cutoff and the ability of PCA3 to predict tumor aggressiveness still remain highly controversial." (PMID 25651917, 2015). "We showed that PHI and urinary PCA3 and T2 scores are predictors of PCa pathological characteristics at radical prostatectomy such as tumor volume <0.5 mL, extracapsular extension and tumor multifocality." (PMID 25079439, 2014). "Several studies investigated the role of prostate cancer antigen 3 (PCA3) in the insignificant cancer diagnosis and some of them demonstrated a significant correlation between PCA3 score and tumor volume, extraprostatic extension, and Gleason score." (PMID 27351008, 2014). "Using a nested PCR-based approach, we were able to show that tumour exosomes carry genetic information specific for PCa, and as a proof-of-principle we used tumour exosomes to detect two PCa mRNA biomarkers, PCA-3 and TMPRSS2:ERG." (PMID 19401683, 2009). "We believe that the PCA3 is more specific for tumor detection than the FOLH1 marker, which presents a high variation on gene expression among PCa and BPH patients and its utilization as a biomarker is highly controversial (unpublished data)." (PMID 18823560, 2008). "Furthermore, EV RNA biomarkers showed promising predictive values in PCa staging and progression: serum miR−141 and miR−375, along with urine miR−141 and PCA3 lncRNA, correlated with higher GS, advanced tumour stages, and metastatic status." (PMID 41340217, 2025). "The current investigation demonstrates that PCA3 and CBR3-AS1 may play a carcinogenic role in individuals with GC since tumor tissue showed higher levels of PCA3 and CBR3-AS1 expression than marginal tissues." (PMID 40356687, 2025). "The fact that knocking down PCA3 reduces AR signaling, as well as cell growth and survival, suggests that modulating AR signaling in tumor cells may be possible by overexpression of PCA3." (PMID 39512820, 2024). "We did not see any association between tumor PCA3 expression and biochemical recurrence in this particular grade and stage setting." (PMID 36645410, 2023). "Overall, the findings support the mechanistic role of a tumor-specific molecular axis in which PCA3 acts as dominant-negative oncogene and PRUNE2 as a tumor suppressor gene in human prostate cancer and indicate that the interplay between these genes is dysregulated early in prostate cancer." (PMID 36645410, 2023). "Here, we assessed the tumor and control adjacent normal prostatic glandular tissue expression of the lncRNA PCA3 and the protein-coding PRUNE2 gene in two independent retrospective cohorts of patients with primary organ-confined prostate cancer after treatment by radical prostatectomy." (PMID 36645410, 2023). "Comparing tumor gene expression across different tumor pathological stages, PCA3 expression was higher in pT2 tumors (median: 12.6; IQR: 11.2–13.8) than in tumors that were pT3 (median: 12.2; IQR: 9.7–13.6, [p-value = 0.01]) or pT4 (median: 12.1; IQR: 9.6–12.7, [p-value = 0.61])." (PMID 36645410, 2023). "Integrative analysis of tumor-infiltrating CD8+ T-cell abundance and overexpressed oncogene candidates showed that MCL cases with high ratio CD8+ T-cells and low expression of FTX or PCA3 can potentially predict high-risk MCL patients." (PMID 36359790, 2022). "Prostate cancer antigen 3 (PCA3) is a tumor marker, is overexpressed in prostate cancer." (PMID 35590912, 2022). "Notably, the expression of PCA3 in PCa tissue was significantly lower in patients who had died of their tumor (AUC of 0.98 [0.96–1] and 0.98 [0.95–1] for TAPIR-1 and -2, respectively versus AUC of 0.80 [0.68–0.91] for PCA3)." (PMID 32365858, 2020). "PCA3 is found to be upregulated in prostate tumors in comparison to non-tumor cells." (PMID 31850193, 2019).